POLRMT (RNA polymerase mitochondrial)
Diseases named in the same sentence as POLRMT in open-access papers (continued):
Sharing a sentence is not in itself a finding about the gene and the disease.
prostate carcinoma (2 papers, 2023 to 2024). A carcinoma that arises from epithelial cells of the prostate gland. "In vivo, intratumoral injection of POLRMT shRNA adeno-associated virus impeded prostate cancer xenograft growth in nude mice." (PMID 37816734, 2023). "Together, overexpressed POLRMT is an important mitochondrial protein for prostate cancer cell growth, representing a novel and promising diagnostic and therapeutic oncotarget." (PMID 37816734, 2023). "Therefore, overexpressed POLRMT is important for prostate cancer cell growth, representing as a novel diagnostic and therapeutic target." (PMID 37816734, 2023). "Inhibition of POLRMT by IMT1 also impaired mitochondrial functions in primary prostate cancer cells, resulting in mitochondrial depolarization, ROS production, and ATP reduction." (PMID 37816734, 2023). "Considering the POLRMT is a mitochondrial protein, mitochondrial fraction lysates of the prostate cancer cells/epithelial cells were separated." (PMID 37816734, 2023). "TCGA results show that POLRMT transcripts are increased in prostate cancer tissues and POLRMT overexpression correlated with poor overall survival of the patients." (PMID 37816734, 2023). "At last, we tested the potential effect of IMT1, the first-in-class POLRMT inhibitor, in prostate cancer cells." (PMID 37816734, 2023). "In primary prostate cancer cells, POLRMT shRNA or KO led to mitochondrial depolarization, ROS production, mitochondria complex I inhibition, and ATP reduction." (PMID 37816734, 2023). "Contrarily, prostate cancer cell proliferation and migration were strengthened after ectopic POLRMT overexpression." (PMID 37816734, 2023). "Further TCGA PRAD analyses showed that expression of POLRMT in prostate cancer tissues (n = 52) was significantly higher than that in the matched adjacent normal tissues (n = 52)." (PMID 37816734, 2023). "High POLRMT expression in prostate cancer tissues predicted poorer overall (area under curve/AUC = 0.739)." (PMID 37816734, 2023). "mRNA expression of key mitochondrial genes, including NDUFB8, UQCRC2, and COXI, was decreased with POLRMT silencing or inhibition, but increased with POLRMT overexpression in prostate cancer cells." (PMID 37816734, 2023). "In the prostate cancer tissues, POLRMT mRNA expression was significantly higher than that in the normal tissues." (PMID 37816734, 2023). "In patient-derived prostate cancer cells (“pCan1” and “pCan2”, from Dr. Mi) and immortalized cell lines (PC-3/LNCaP), POLRMT mRNA expression is significantly higher than that in primary human prostate epithelial cells (“pEpi”, from Dr. Mi)." (PMID 37816734, 2023). "The results of the present study proposed an important role of the mitochondrial protein POLRMT in prostate cancer." (PMID 37816734, 2023). "POLRMT silencing, oxidative stress, and ATP depletion were detected in POLRMT shRNA-treated prostate cancer xenograft tissues." (PMID 37816734, 2023). "The EdU-positive nuclei ratio was substantially decreased after POLRMT silencing/KO in pCan1 cells, suggesting that genetic POLRMT depletion inhibited prostate cancer cell proliferation." (PMID 37816734, 2023). "In the other patient-derived prostate cancer cells (“pCan2”) and immortalized lines (PC-3/LNCaP), the lentiviral shPOLRMT-S1 was stably transduced to silence POLRMT." (PMID 37816734, 2023). "The top fifty CEGs positively-correlating with POLRMT in the prostate cancer tissues were shown in the heat map." (PMID 37816734, 2023). "Conversely, prostate cancer cell proliferation, migration, and ATP contents were strengthened following ectopic POLRMT overexpression." (PMID 37816734, 2023). "Next, the Kaplan-Meier survival analysis was carried out and results demonstrated that high POLRMT expression in prostate cancer was correlated with poor overall survival (P = 0.008)." (PMID 37816734, 2023).
prostate carcinoma (continued). "Analyzing The Cancer Genome Atlas (TCGA) prostate cancer cohort (TCGA PRAD) revealed that the number of POLRMT transcripts in prostate cancer tissues (“Tumor”, n = 501) was significantly higher than that in the normal prostate tissues (“Normal”, n = 52)." (PMID 37816734, 2023). "IMT1 (inhibitor of mitochondrial transcription 1), the first-in-class POLRMT inhibitor, inhibited prostate cancer cell growth in vitro and in vivo." (PMID 37816734, 2023). "In vivo, intratumoral injection of POLRMT shRNA-expressing AAV impeded prostate cancer xenograft growth in nude mice." (PMID 37816734, 2023). "POLRMT mRNA and protein levels were upregulated in local prostate cancer tissues and different primary/immortalized prostate cancer cells." (PMID 37816734, 2023). "The protein expression of POLRMT in the fresh tissue lysates was examined by Western blotting assays and results confirmed POLRMT protein upregulation in prostate cancer tissues of four representative patients (“Patient-1” to “Patient-4”)." (PMID 37816734, 2023). "Importantly, the mitochondrial protein POLRMT was upregulated in primary/immortalized prostate cancer cells and its expression is low in pEpi cells." (PMID 37816734, 2023). "Next, the expression of POLRMT in different prostate cancer cells was examined as well." (PMID 37816734, 2023). "Importantly, in POLRMT-silenced prostate cancer xenograft tissues, NDUFB8, UQCRC2, and COXI downregulation as well as oxidative stress, lipid peroxidation, and ATP reduction were detected as well." (PMID 37816734, 2023). "Importantly, IMT1, the first-in-class POLRMT inhibitor, inhibited prostate cancer cell growth in vitro and in vivo." (PMID 37816734, 2023). "Here we found that POLRMT is key in maintaining mitochondrial functions in prostate cancer cells." (PMID 37816734, 2023). "The expression levels of POLRMT in local prostate cancer tissues were explored as well." (PMID 37816734, 2023). "In addition, POLRMT mRNA and protein levels are significantly elevated in local prostate cancer tissues and in different primary/immortalized cancer cells." (PMID 37816734, 2023). "Together, POLRMT depletion impaired mitochondrial functions in prostate cancer cells." (PMID 37816734, 2023). "Thus, the studies indicate that POLRMT upregulation in prostate cancer correlates with poor survival." (PMID 37816734, 2023). "POLRMT silencing led to significant mitochondrial depolarization and ROS production in the primary/established prostate cancer cells, evidenced by increasing in JC-1 green fluorescence monomer intensity and CellROX red fluorescence intensity increasing, respectively." (PMID 37816734, 2023). "We thus explored whether POLRMT depletion using genetic means affected mitochondrial functions in prostate cancer cells." (PMID 37816734, 2023). "Thus, POLRMT depletion impaired mitochondrial functions and impeded prostate cancer cell growth in vitro and in vivo." (PMID 37816734, 2023). "Moreover, proliferation (EdU-nuclei ratio) and migration were significantly inhibited after POLRMT silencing in the prostate cancer cells." (PMID 37816734, 2023). "Therefore, overexpressed POLRMT is an important mitochondrial protein for prostate cancer cell growth, representing as a novel and promising diagnostic/therapeutic target." (PMID 37816734, 2023). "Moreover, POLRMT depletion resulted in robust inhibition of prostate cancer cell viability, proliferation, and migration, and provoked apoptosis." (PMID 37816734, 2023). "We next tested whether POLRMT depletion altered prostate cancer cell behaviors." (PMID 37816734, 2023). "Thus, POLRMT depletion induced apoptosis activation in prostate cancer cells." (PMID 37816734, 2023). "Genetic depletion of POLRMT, using viral shRNA or CRISPR/Cas9 method, resulted in substantial inhibition on prostate cancer cell viability, proliferation, and migration, while provoking apoptosis." (PMID 37816734, 2023).
prostate carcinoma (continued). "Genetic depletion of POLRMT, using viral shRNA or CRISPR/Cas9 gene editing methods, impaired mitochondrial functions in prostate cancer cells, leading to mitochondrial depolarization, oxidative stress, mitochondria complex I inhibition, and ATP depletion." (PMID 37816734, 2023). "The Cancer Genome Atlas prostate cancer cohort (TCGA PRAD) shows that POLRMT mRNA expression is upregulated in prostate cancer tissues and POLRMT upregulation is correlated with poor patients’ survival." (PMID 37816734, 2023). "Nevertheless, the expression and potential functions of the mitochondrial protein POLRMT in prostate cancer have not been extensively studied thus far." (PMID 37816734, 2023).
breast invasive carcinoma (1 paper, 2016). "For example, datasets for glioblastoma and breast invasive carcinoma reveal a significant correlation between MYC and POLRMT, with p values of < 0.001 and .002, respectively." (PMID 27590350, 2016).
Burkitt lymphoma (1 paper, 2016). A rare form of malignant mature B-cell non-Hodgkin lymphoma. "In order to assess POLRMT expression in a variety of cell lines exhibiting endogenous MYC overexpression, the human Burkitt's lymphoma cell line Raji was used in addition to the epithelial line H1299 to represent a lymphoid model with MYC translocation." (PMID 27590350, 2016).
cardiomyopathy (1 paper, 2024). A disease of the heart muscle or myocardium proper. "Like POLRMT and TEFM, MRPP3/PRORP and ELAC2 are essential proteins with non-redundant functions that cause very early cardiomyopathy and premature death in mice that model that seen in the patient mutations." (PMID 38779771, 2024).
Cockayne syndrome (1 paper, 2025). A multisystem condition characterized by short stature, a characteristic facial appearance, premature aging, photosensitivity, progressive neurological dysfunction, and intellectual deficit. "This novel multiprotein complex is composed of HTT, mitochondrial RNA polymerase (POLRMT), mitochondrial DNA polymerase gamma, Cockayne syndrome proteins, PNKP and other mitochondria-specific transcription factors." (PMID 40777236, 2025).
diabetic retinopathy (1 paper, 2024). "Significantly elevated expression of POLRMT was observed in the retinal tissues of streptozotocin-induced diabetic retinopathy (DR) mice." (PMID 38907279, 2024). "This was further corroborated by the elevated levels of both POLRMT mRNA and protein expression, along with an increase in the expression of POLRMT-dependent genes, in the retinal tissues of murine models with STZ-induced diabetic retinopathy (DR)." (PMID 38907279, 2024).
hepatitis C infection (1 paper, 2017). "Cell culture and biochemical experiments have also demonstrated that antiviral ribonucleoside drugs developed to treat hepatitis C infection act as off-target substrates for POLRMT, the mitochondrial RNA polymerase and primase." (PMID 29214156, 2017).
immune deficiency (1 paper, 2021). "In vivo, intratumoral injection of POLRMT shRNA adeno-associated virus (AAV) potently inhibited NSCLC xenograft growth in severe combined immune deficiency mice." (PMID 34326320, 2021).
Insulin resistance (1 paper, 2020). Increased resistance towards insulin, that is, diminished effectiveness of insulin in reducing blood glucose levels. "The induction of VPS8, POLRMT, and IGFBP5 GPs at the end of 4th week during 4-week intermittent fasting preceded the significant reduction in insulin resistance estimated by HOMA-IR that occurred 1 week after 4-week intermittent fasting." (PMID 33110154, 2020).
lung adenocarcinoma (1 paper, 2023). A carcinoma that arises from the lung and is characterized by the presence of malignant glandular epithelial cells. "The present study investigated the impact of POLRMT expression and function on lung adenocarcinoma (LUAD) patients." (PMID 37283308, 2023).
nemaline myopathy (1 paper, 2023). Nemaline myopathy (NM) encompasses a large spectrum of myopathies characterized by hypotonia, weakness and depressed or absent deep tendon reflexes, with pathologic evidence of nemaline bodies (rods) on muscle biopsy. "In detail, the NEB mutation may cause Nemaline myopathy, and POLRMT is a key enzyme for transcription of the mitochondrial genome." (PMID 37860673, 2023).
oral cancer (1 paper, 2021). "Similarly, 24 and 72 h POMx treatment inhibits mRNA and protein expressions for mitochondrial biogenesis of gene expression (TFB2M, TFAM, POLRMT, and TUFM) in oral cancer cells." (PMID 34356350, 2021).
polymicrogyria (1 paper, 2026). A developmental brain abnormality characterized by an excessive amount of small convolutions on the surface of the brain and cognitive dysfunction. "Moreover, polymicrogyria, corpus callosum agenesis, heterotopia, and plexus cysts reported in P6 are unusual findings for mitochondrial disorder and may indicate other unidentified disease mechanisms besides the POLRMT mitochondrial pathology." (PMID 40583167, 2026).
small cell carcinoma (1 paper, 2023). A neuroendocrine carcinoma composed of small malignant cells which are often said to resemble "oat cells" under the microscope. "In recent studies, POLRMT expression promoted non‐small cell cancer cell proliferation in cell lines and xenografts." (PMID 37283308, 2023).
cancer (23 papers, 2016 to 2025). A tumor composed of atypical neoplastic, often pleomorphic cells that invade other tissues. "Any disruption or malfunction of POLRMT has been associated with a range of mitochondrial disorders and diseases, such as cancer." (PMID 39227564, 2024). "Our analysis revealed notable distribution patterns of the POLRMT gene across various cell types, with a particular focus on epithelial cells (cancerous cells) and cancer-associated endothelial cells." (PMID 39227564, 2024). "Dysregulation or malfunction of POLRMT has been implicated in various mitochondrial disorders and diseases (including cancer)." (PMID 38228583, 2024). "A number of these newly liganded cysteines are on proteins associated with gene expression and regulations, as well as cancer drivers including POLRMT and RAD21 which are potential hotspots for therapy." (PMID 37322008, 2023). "Despite this knowledge, the potential for targeting POLRMT and associated processes in cancer has only recently been explored." (PMID 37371693, 2023). "We found that POLRMT expression was related to multiple gene sets and was linked to immune infiltration, opening promising avenues of investigation in cancer research." (PMID 37283308, 2023). "The high expression of POLRMT is directly associated with poor prognosis in cancer patients." (PMID 38589371, 2024). "Mutations in the gene encoding POLRMT directly impact transcription levels, thereby causing dysfunction in key mitochondrial processes such as oxidative phosphorylation, eventually leading to the development of malignant tumors." (PMID 37283308, 2023). "Comparing p0 cells to ClpP agonist- or POLRMT inhibitor-treated cells may help establish if the loss of mtDNA is a critical and common anti-cancer response to these treatments." (PMID 37371693, 2023). "A high degree of oxidative phosphorylation can often be observed in cancer models, so we speculated that POLRMT may be associated with cancer progression." (PMID 33923185, 2021). "Elevated POLRMT levels are found in several cancers and in mouse models with severe mitochondrial dysfunction." (PMID 41107062, 2025). "Treatment with the POLRMT inhibitor led to downregulation of mitochondrial complex I activity in the primary cancer cells, which was accompanied with ATP reduction." (PMID 39227564, 2024). "The CMS4 subtype is known for its mesenchymal characteristics and poor prognosis, implicating POLRMT as a potential biomarker or therapeutic target in this aggressive cancer subtype." (PMID 39227564, 2024). "The significant role of POLRMT in cancer makes it an emerging therapeutic target for cancer treatment." (PMID 38589371, 2024). "Within this subgroup, POLRMT expression was found to be significantly elevated in cancer-related proliferative endothelial cell subtypes." (PMID 39227564, 2024). "Together, SUCLG1 connects succinyl-CoA with POLRMT succinylation to modulate mitochondrial function and cancer development." (PMID 38649537, 2024). "Though ClpP agonists and POLRMT inhibitors effectively reduce cancer cell proliferation, much remains to be discovered about the mechanism of action of these compounds." (PMID 37371693, 2023). "While this review aimed to emphasize the surprising similarities between these anti-cancer approaches, how ClpP agonists and POLRMT inhibitors compare to other mitochondria-targeting drugs also remains to be determined." (PMID 37371693, 2023). "Additional studies need to be completed to determine if reliance on aerobic respiration is a key factor that influences the responsiveness of cancer cells to ClpP agonists or POLRMT inhibitors." (PMID 37371693, 2023). "ClpP agonists and POLRMT inhibitors have been shown to impair cellular proliferation in multiple cancer cell lines and models." (PMID 37371693, 2023).